TRMT2B (tRNA methyltransferase 2B)
Description:
Mitochondrial S-adenosyl-L-methionine-dependent methyltransferase that catalyzes the formation of 5-methyl-uridine in tRNAs and 12S rRNA. Catalyzes the methylation of uridine at position 54 (m5U54) in all tRNAs. Specifically methylates the uridine in position 429 of 12S rRNA (m5U429). Does not affect RNA stability or mitochondrial translation.
Synonyms: CXorf34; FLJ12687; dJ341D10.3
Tractability: PROTAC: ubiquitination databases record sites on it; its protein half-life has been measured.
Gene: Protein-coding gene on chromosome X (101,009,346 to 101,052,135, reverse strand). Ensembl gene ENSG00000188917.
Subcellular location: Mitochondrion; Mitochondrion matrix (Isoform 1)
Subcellular location (Human Protein Atlas): Nucleoplasm; Nuclear bodies
Gene Ontology:
Molecular function: protein binding; rRNA (uridine-C5-)-methyltransferase activity; tRNA (uracil(54)-C5)-methyltransferase activity, S-adenosyl methionine-dependent; RNA methyltransferase activity
Biological process: RNA processing
Cellular component: mitochondrial matrix; mitochondrion
Homologues: Orthologues: chimpanzee TRMT2B (99% identical), macaque TRMT2B (95% identical), pig TRMT2B (86% identical), rabbit TRMT2B (82% identical), mouse Trmt2b (75% identical), zebrafish trmt2b (49% identical), tropical clawed frog trmt2b (48% identical). Paralogues in human: TRMT2A (37% identical).
Diseases named in the same sentence as TRMT2B in open-access papers:
TRMT2B is named in the same sentence as 3 diseases in open-access papers, as found by Europe PMC text mining. Sharing a sentence is not in itself a finding about the gene and the disease. The quoted sentences say what the papers report.
glioma (3 papers, 2021 to 2025). A benign or malignant brain and spinal cord tumor that arises from glial cells (astrocytes, oligodendrocytes, ependymal cells). "Results revealed that MRM2 and TRMT2B were differentially expressed between NBTs, low-grade glioma tissues, and high-grade glioma tissues." (PMID 34566979, 2021). "Our findings revealed that MRM2, NSUN4, TFB1M, and TRMT2B were correlated significantly with most immunomodulators in glioma, whereas MRM1 and RPUSD4 were correlated negatively." (PMID 34566979, 2021). "Results revealed that TRMT2B, TRMT11, METTL8, TRMT6, and TRUB2 were upregulated in glioma, while METTL6 was downregulated." (PMID 38824202, 2024). "Moreover, we observed protein expression of MRM1, MRM3, TRMT2B, and NSUN4 to be significantly different between low- and high-grade gliomas, whereas other regulators could not be obtained due to lack of data." (PMID 34566979, 2021).
amyotrophic lateral sclerosis (2 papers, 2025). Amyotrophic lateral sclerosis (ALS) is a neurodegenerative disease characterized by progressive muscular paralysis reflecting degeneration of motor neurons in the primary motor cortex, corticospinal tracts, brainstem and spinal cord. "TRMT2B, which installs m5U at mt-tRNA position 54 and in mt-12S rRNA, has been implicated in amyotrophic lateral sclerosis (ALS)." (PMID 41465450, 2025). "Mutations in tRNA methyltransferase 2B (TRMT2B) have been identified in patients with amyotrophic lateral sclerosis (ALS)." (PMID 39719325, 2025).
cancer (2 papers, 2024 to 2025). A tumor composed of atypical neoplastic, often pleomorphic cells that invade other tissues. "However, limited studies have examined the effect of TRMT2B, TRMT11, and TRUB2 in cancers." (PMID 38824202, 2024). "While the roles of TRMT2B and TYW1 in cancer are not yet defined, their significant coefficients in our model suggest potential functional importance that warrants further study." (PMID 40561176, 2025).